SLC35G2 (solute carrier family 35 member G2)
Synonyms: TMEM22; MGC3295; DKFZp564K2464
Tractability: Antibody: UniProt places it where antibodies can reach, with high confidence; its Gene Ontology location is reachable by antibodies, with high confidence; UniProt predicts a signal peptide or a membrane-spanning region; the Human Protein Atlas places it where antibodies can reach. PROTAC: ubiquitination databases record sites on it.
Gene: Protein-coding gene on chromosome 3 (136,818,463 to 136,857,531, forward strand). Ensembl gene ENSG00000168917.
Subcellular location: Cell membrane; Cytoplasmic vesicle, secretory vesicle, synaptic vesicle membrane
Subcellular location (Human Protein Atlas): Plasma membrane
Gene Ontology:
Molecular function: protein binding
Cellular component: Golgi apparatus; plasma membrane; synaptic vesicle membrane; membrane
Genetic constraint (gnomAD): Loss-of-function variants: 20 observed, 28.24 expected, observed/expected ratio (o/e) 0.71, 90% interval 0.5 to 1.03. The upper end of that interval is the gene's LOEUF score, 1.03, which puts it in group 4 of 6, group 1 being the genes least tolerant of losing a copy. Missense variants: 416 observed, 515.6 expected, observed/expected ratio (o/e) 0.81, 90% interval 0.74 to 0.88. Synonymous variants: 148 observed, 173.32 expected, observed/expected ratio (o/e) 0.85, 90% interval 0.75 to 0.98.
Homologues: Orthologues: chimpanzee SLC35G2 (99% identical), macaque SLC35G2 (98% identical), dog SLC35G2 (97% identical), pig SLC35G2 (96% identical), guinea pig SLC35G2 (95% identical), mouse Slc35g2 (92% identical), rat Slc35g2 (92% identical), tropical clawed frog slc35g2 (79% identical), rabbit SLC35G2 (78% identical), zebrafish slc35g2b (73% identical), zebrafish slc35g2a (70% identical), Drosophila melanogaster CG5281 (16% identical). Paralogues in human: SLC35G6 (24% identical), SLC35G4 (24% identical), SLC35G5 (23% identical), SLC35G3 (23% identical), SLC35G1 (18% identical).
Diseases named in the same sentence as SLC35G2 in open-access papers:
SLC35G2 is named in the same sentence as 14 diseases in open-access papers, as found by Europe PMC text mining. Sharing a sentence is not in itself a finding about the gene and the disease. The quoted sentences say what the papers report.
clear cell renal cell carcinoma (2 papers, 2022 to 2025). "For instance, overexpression of SLC35G2/TMEM22 (P = 1.16 × 10−5) has been linked to the progression of clear cell renal cell carcinoma." (PMID 40279344, 2025).
colorectal cancer (2 papers, 2019 to 2022). A primary or metastatic malignant neoplasm that affects the colon or rectum. "NCK1 is adaptor protein that is downstream of receptor tyrosine kinase and STAT3 signaling; both NCK1 and the other correlated gene, SLC35G2, may be involved in colorectal cancer pathogenesis." (PMID 30767760, 2019).
Allergy (1 paper, 2025). An allergy is an immune response or reaction to substances that are usually not harmful. "These measures will enhance the clinical value of LDHC and SLC35G2 as actionable biomarkers for food allergy management." (PMID 41153772, 2025). "This dual-dataset methodology not only strengthens the reliability of the findings but also emphasizes the translational potential of epigenetic biomarkers including LDHC and SLC35G2 in clinical implementations for food allergy diagnosis and treatment." (PMID 41153772, 2025). "Solute carrier transport proteins, such as SLC35G2, regulate lymphocyte communication and maturation, mechanisms essential for immune balance homeostasis and may influence allergic reactions." (PMID 41153772, 2025).
epilepsy (1 paper, 2021). A brain disorder characterized by episodes of abnormally increased neuronal discharge resulting in transient episodes of sensory or motor neurological dysfunction, or psychic dysfunction. "Herein, we identified seven genes (NCL, SEPHS2, PA2G4, SLC35G2, MYO1C, GPR158, and POU3F1) with de novo variants but unknown pathogenicity that were not previously associated with epilepsy." (PMID 34489640, 2021).
food allergy (1 paper, 2025). Gastrointestinal disturbances, skin eruptions, or shock due to allergic reactions to allergens in food. "This validation analysis establishes LDHC and SLC35G2 methylation signatures as reproducible biomarker candidates for food allergy diagnosis." (PMID 41153772, 2025). "LDHC and SLC35G2 methylation profiles show promise as biomarkers for food allergy diagnosis and for predicting treatment response." (PMID 41153772, 2025).
Hepatitis (1 paper, 2022). Inflammation of the liver. "In addition, most of these genes have a risk coefficient greater than 0 (AC008271.1, C11orf53, F2RL2, GBP5, LUCAT1, RP11‐149I23.3, RP11‐383 J24.1 and SLC35G2), except for CASP8 and RP11‐114B7.6, suggesting that these genes are adverse prognostic factors in hepatitis‐positive HCC patients." (PMID 35637633, 2022).
melanoma (1 paper, 2015). A malignant, usually aggressive tumor composed of atypical, neoplastic melanocytes. "Differential regulation in SLC35G2 expression in intrahepatic cholangiocarcinoma and promoter hypermethylation of SLC35G2 in melanoma were previously reported." (PMID 26169495, 2015).
tumor (5 papers, 2012 to 2025). "Here, we also observe up-regulation of SLC35G2 expression in our tumor set." (PMID 26169495, 2015).
SLC35G2 also shares sentences with these, for which no sentence is quoted: cancer (3 papers); glioblastoma (3); renal cell carcinoma (2); bladder cancer (1); glioma (1); neuroblastoma (1).